MMP7 (matrix metallopeptidase 7)
Diseases named in the same sentence as MMP7 in open-access papers (continued):
Sharing a sentence is not in itself a finding about the gene and the disease.
tumor (continued). "To further study the correlation between CTHRC1 and MMP7 as well as MMP9 in fresh primary tumour tissues, we measured the expression of CTHRC1 and MMPs by performing reverse dot blot hybridization." (PMID 29631554, 2018). "Western blotting revealed that the expression of β‐catenin, TCF1, cyclin D1, AXIN2 and MMP7 was remarkably reduced in shTRIM32‐inoculated tumour tissues." (PMID 30079558, 2018). "The upregulation of MMP7 also underscores the significance of cell–matrix interactions in tumor development; however, its less consistent prognostic impact seen in earlier studies delays the elucidation of its role in the pathobiology of NSCLC." (PMID 29483918, 2018). "Expression of MMP7 in mice promotes tumour development whereas reduction of MMP7 expression diminishes tumour incidence, although the exact mechanism is yet to be defined." (PMID 29674723, 2018). "FBLN5 was silenced by promoter hypermethylation, and this resulted in activation of MMP7 and increased tumor invasion." (PMID 29581841, 2018). "Extracellular proteolytic enzymes, like MMP-7, are important modifiers of the tumor microenvironment to switch from a largely indolent pathology to active metastasis in multiple cancers including PCa65–67." (PMID 29740048, 2018). "We demonstrated that PD98039, which serves as an ERK inhibitor, successfully up-regulated the level of E-cadherin, and down-regulated the level of MMP7 in vitro, leading directly to decreased migration and invasion in tumor cells." (PMID 28796798, 2017). "MMP7 plays an important role in tumor metastasis and regulation of cell migration through the breakdown of the extracellular matrix." (PMID 28796798, 2017). "In the current study, the combination of both comparative tumor markers with MMP-7 had unquestionably higher NPV value ~100%." (PMID 28662671, 2017). "In line with this, knockdown of CD82 expression by sh/CD82 or miR-197 in Drosha-silenced MGC-803 cells resulted in the increased expression of p-EGFR, p-ERK1/2 and MMP7, which rendered the tumor cells with a marked invasive potential." (PMID 28252644, 2017). "Matrix metalloproteinases (MMPs), a family of zinc-binding proteins including MMP2 and MMP7, have been shown to play a central role in tumor cell invasion and metastasis due to their ability to degrade the extracellular matrix." (PMID 28968424, 2017). "This inhibition of Wnt signaling within tumor cells led to reduced levels of β-catenin, which caused a reduction in the expression of VEGF, matrix metalloproteinase (MMP)-7 and Cyclin D1, as well as triggering apoptosis of the tumor cells." (PMID 28974047, 2017). "In the present study, PLCD1, pERK1/2, active-β-catenin and MMP7 protein levels were measured by immunohistochemistry (IHC) in these tumours." (PMID 28423710, 2017). "MMP7 is a matrix metallopeptidase that is involved in tumour progression by influencing cell invasion, metastasis, and the epithelial-to-mesenchymal transition." (PMID 28423710, 2017). "There are many validated miRNA-148a’s target genes contributing to the tumor metastatic behavior, including MMP7, ROCK1, SMAD2, Met and cholecystokinin B receptor (CCK-BR)." (PMID 28199399, 2017). "E-cadherin and MMP7 are thought to promote tumor metastasis and progression in a variety of human cancers by inducing EMT." (PMID 28796798, 2017). "Taken together, our results identify a novel anti-tumor role for MMP-7 in vivo and highlight the importance of elucidating the function of individual MMPs in a disease-specific context." (PMID 28241871, 2017). "The mRNA levels of c-myc, Birc5, Cd44, Lgr5, Tcf7, Mmp7, and Ephb3 were significantly increased in tumor area compared with non-tumor area." (PMID 28710436, 2017). "Strong correlations between MMP-7 overexpression and invasion are observed in cancer cell lines and mouse models across most tumor types." (PMID 29234409, 2017). "MMP7 is a matrix metallopeptidase involved in invasion and metastasis in multiple cancers including breast cancer." (PMID 28827662, 2017).
tumor (continued). "Our findings reveal for the first time that the crosstalk between ARF and MMP7 in nucleus contributes to ECM network in tumor microenvironments in vivo, implicating a novel therapeutic target for advanced PCa treatment." (PMID 27356744, 2016). "It has been shown that β-catenin can regulate WNT11, Cyclin D1, and MMP7 in many tumor cells, and so we next examined the role of CTNND1-mediated modulation of these genes." (PMID 27193094, 2016). "MMP7, a soluble metalloproteinase and an established WNT/β-catenin target gene, has been repeatedly linked to tumor progression and metastasis in various types of cancers." (PMID 27835587, 2016). "Oncogenic functions of MMP7 rely on different interactions between tumor cells, tumor microenvironment and immune system." (PMID 27431388, 2016). "As downstream effectors of the Wnt/β-catenin pathway, c-myc, CyclinD1, MMP-2, and MMP-7 promote tumor cell proliferation, cell cycle, and migration." (PMID 27533254, 2016). "Given the decisive role of ARF and MMP7 interactions on tumor progression in vitro and in vivo, we examined the correlation between MMP7 and ARF in human PCa specimens." (PMID 27356744, 2016). "We also investigated the role of miR-329 on expression of MMP-9 and MMP-7, which all play a key role on tumor metastasis, and results indicated miR-329 inhibited the mRNA expression of MMP-9 and MMP-7 both in A549 and H1299 cells." (PMID 26909600, 2016). "In contrast, the positive expression of MMP-7 was observed mainly in tumor cells (96.55%), less in the stromal cells (55.17%), as compared to the normal pancreas (93.10%)." (PMID 27429508, 2016). "MMP-7 is one of the most important target genes downstream of β-catenin signaling and plays a crucial role in promoting tumor cell migration and invasion." (PMID 27608843, 2016). "We also investigated the role of miR-134 on expression of MMP-7 and MMP-9, which all play a key role on tumor metastasis, and results indicated miR-134 inhibited the protein expression of MMP-7 and MMP-9 both in A549 and SPC-A-1 cells." (PMID 27166267, 2016). "Directional movement of tumor cells was observed by confocal immunofluorescence microscopy and quantitative confocal-video-microscopy while matrigel-invasion was studied by MMP7-specific casein-zymography." (PMID 27281609, 2016). "Western blotting demonstrated that levels of the tumor invasion and metastasis-associated proteins, MMP2 and MMP7, were increased or decreased in miR-520g overexpressing or downregulated EOC cells, respectively." (PMID 27049921, 2016). "In contrast to other MMPs, MMP7 is mainly secreted by cancer cells and activated through cytokines or other MMPs, which are released by tumor stromal cells." (PMID 27431388, 2016). "In our study, the positive MMP-7 expression was present in most cases in tumor cells, in more than half of the cases in the stroma, and in only two cases in normal pancreatic ducts." (PMID 27429508, 2016). "The expression of MMP-7 in tumor cells was found to positively correlate with the presence of necrosis and negatively correlate with MVD (R = 0.402, p = 0.031; R = −0.682, p = 0.000)." (PMID 27429508, 2016). "We also investigated the role of miR-875-5p on expression of MMP-7 and MMP-9, which all play a key role on tumor metastasis, and results indicated miR-875-5p inhibited the protein expression of MMP-7 and MMP-9 both in HCT116 and SW480 cells." (PMID 27302926, 2016). "Consistently, in human HCCA tissues, DKK1 level was positively correlated with β-catenin and MMP-7 expression, as well as tumor hilar lymphatic metastasis." (PMID 27608843, 2016). "When datasets with clinical parameters were selected for the analysis, stratification for tumour grade or recurrence further identified MMP7 selective expression." (PMID 25596746, 2015).
tumor (continued). "Among target genes of TCF/LEF family, cyclin D1 and c-myc are responsible for the decision between proliferation and apoptosis in the cells, and matrix metalloproteinase-7 (MMP-7) is related with tumor metastasis." (PMID 26289446, 2015). "Our in vitro data further showed that GR127935 functions as a tumor suppressor via Axin1/β-catenin/MMP-7 pathway in the cell cycle, proliferation, and invasion." (PMID 26214021, 2015). "As expected, highly expressed ETV4 in CRMAC increased MMP-7, N-cadherin and vimentin whereas decreased E-cadherin, which promoted tumor invasion." (PMID 26356816, 2015). "The bioinformatics data highlighted the efficacy of MMP7 to specifically subselect tumours with higher aggressiveness, suggesting a potential role of negative prognostic marker." (PMID 25596746, 2015). "In some cases, human pro-MMP1, 2, and 9 can be activated by MMP-7, which further facilitate the metastasis of tumor cells." (PMID 25823818, 2015). "In contrast to other MMPs, which are usually expressed in stromal tissue, MMP-7 is expressed mainly on the tumor cell surface." (PMID 26699938, 2015). "This analysis highlighted the efficacy of MMP7 to specifically subselect tumours with higher aggressiveness, suggesting a potential role of negative prognostic marker." (PMID 25596746, 2015). "The expression of KAI1/CD82, CD44, MMP7 and β-catenin is related to tumor metastasis and prognosis in CRC." (PMID 26408312, 2015). "Conventional tumor markers MMP7 and OPN were found expressed in 63% and 79% of the tumors and in 4% and 1% of the normal tissues, respectively." (PMID 26517682, 2015). "Concurrently, inhibiting β-catenin expression under hypoxic conditions reduced the size of the xenograft tumor as well as uPA and MMP-7 protein expression levels." (PMID 25997455, 2015). "In xenograft tumor model, the MMP-7 and MMP-10 protein expressions were diminished in MLN8237 treated group compared to DMSO by immunohistochemical staining." (PMID 25889801, 2015). "We and others have reported the involvement of MMP-7 in the migration and invasion of different tumor cell types." (PMID 25823818, 2015). "β-catenin then binds to the lymphocyte enhancer factor/T cell-specific transcription factor, activating the target genes, c-myc, cyclin D and MMP7, leading to cellular proliferation and tumor formation." (PMID 25435937, 2015). "HIF-1α, β-catenin, uPA and MMP-7 protein expression levels were highest in the tumor tissue from the hypoxia group and lowest in the interference group." (PMID 25997455, 2015). "Soluble CD44, probably shedding due to increased MMP-7 protease activity, promotes the effect further by inhibiting adhesion of tumor cells." (PMID 25885552, 2015). "Using vector driven RNA interference, it was demonstrated that MMP7 was required for in-vitro cell migration and invasion and tumor formation in vivo." (PMID 25875355, 2015). "Overall, these results indicate that there is a complex relationship between the KAI1/CD82, CD44, MMP7 and β-catenin in tumor progression." (PMID 26408312, 2015). "These activities of MMP-7 have important biological consequences relevant to tumor progression and metastasis." (PMID 25588786, 2015). "The proteins in our classifier are related to the biology of tumor growth and function to sustain proliferation and activate invasion (MMP7 and MMP12), and respond to oxidative stress and deregulation of cellular energetics (CNDP1 and CA6)." (PMID 25114662, 2014). "As the malignancy potential of the tumour increases, the ability of MMP-7 to retard its invasion declines considerably." (PMID 26019601, 2014). "The patterns of immunostaining of MMP-7 and MMP-13 correlated well with Bryne's malignancy grading of tumour structure and nuclear polymorphism, thereby indicating that these MMPs can be relevant in gauging the malignancy potential of OSCC." (PMID 26019601, 2014). "The invasive front of tumor specimens showed a higher MMP7 expression rate compared to other parts of the tumor." (PMID 25919283, 2014).
tumor (continued). "Our data showed that, while MMP9 and MMP15 (MT2-MMP) expression in tumor cells was negligible in both Apcmin/+ and Apcmin/+/Stat3IEC-KO mice, MMP7 expression in tumor cells was significantly lower in Apcmin/+/Stat3IEC-KO mice." (PMID 24995503, 2014). "In human tumors, MMP-7 is produced by stromal cells (macrophages, fibroblasts and endothelial cells) and also by tumor cells." (PMID 25984271, 2014). "The study showed that MMP-7 was significantly higher in both tumor and serum samples from patients with metastatic BUCC than in those without known metastasis." (PMID 25984271, 2014). "The authors revealed that high MMP7 expression was associated with aggressive tumor phenotypes such as TNM stage, depth of tumor invasion, lymph node and distant metastasis." (PMID 25919283, 2014). "Conversely, a high-level synergism was also observed, due to a strong and significant upregulation of numerous canonical EGF-targets with putative tumor-promoting properties such as MMP7, VEGFA, and IL-8." (PMID 23762360, 2013). "Cox multivariate survival rate analysis demonstrated positive correlations between MMP-7 expression level and a high potential for tumor invasion and metastasis, and a poor prognosis." (PMID 23408109, 2013). "MMP-7 expression was demonstrated in endothelial cells of various tumors and was associated with decreased survival suggesting that MMP-7 is involved in tumor angiogenesis." (PMID 24392031, 2013). "Upregulated expression of MMP-7 and downregulated expression of TIMP-2 in CCRCC have significant clinicopathological associations with the aggressiveness observed for this tumor." (PMID 23408109, 2013). "The survival rate in the 5 years following tumor resection was estimated to be 95, 85, 20 and 0% for patients with -, +, ++ and +++ MMP-7 expression, respectively, and 50, 80, 93 and 100% for patients with -, +, ++ and +++ TIMP-2 expression, respectively." (PMID 23408109, 2013). "We observed that in Emory cohort the expression of mRNA for MMP7 was significantly higher in tumors from patients with TNBC as compared to tumor samples from, (a) HR+ patients (3.97 fold; p = 5.14 ×10-20), and (b) HER2+ patients (5.14 fold; p = 6.00 ×10-22)." (PMID 24143235, 2013). "More specifically, tumor-promoting target genes, e.g. MMP7/9, IL-8 and VEGFA, were synergistically upregulated, while intriguingly negative modulators of HH/GLI signaling, such as HHIP and PTCH1, were downregulated." (PMID 23762360, 2013). "Considering that MMP7 is one of the most important target genes downstream of β-catenin/TCF signaling, in addition, MMP7 has been shown to play a crucial role in promoting tumor cell migration and invasion." (PMID 24325363, 2013). "Higher levels of expression of MMP7 mRNA were observed in tumor samples from the TN patients as compared to HR+ and four HER2-amplified patients from St." (PMID 24143235, 2013). "MMP-7 plays a significant role in all stages of tumor progression and is a key player in a wide variety of cancers including, but not limited to, colon, prostate, lung and ovarian." (PMID 23251453, 2012). "MMP-7 is widely expressed in colon adenocarcinomas, but has also been proposed to play a role in the early events of tumor progression since low levels have been detected in 50% of benign adenomas." (PMID 22159423, 2012). "Using a rodent model, we previously identified that MMPs were highly expressed in the tumor-bone microenvironment with subsequent studies revealing that MMPs such as MMP-7 and MMP-9 were largely localized to osteoclasts in this setting." (PMID 22238668, 2012). "MMP-7 is shown to increase tumour cell resistance to chemotherapeutic agents and to decrease tumour cell sensitivity to apoptosis, both of which increase tumour survival." (PMID 22005011, 2011). "These selective effects of MMP7 during tumor progression are similar to those observed during the acquisition of chemoresistance." (PMID 19266094, 2009).
tumor (continued). "In the present work, we demonstrate that MMP7 expression increases when tumor cells acquire resistance to oxaliplatin." (PMID 19266094, 2009). "The involvement of MMP7 in the promotion of a tumor in its early stages has been discussed by several authors." (PMID 19266094, 2009). "Matrix metalloproteinases including MMP7 play important roles in determining tumour invasion and metastasis and MMP7 gene expression correlates with vessel invasion and both lymphatic and hematogenous metastases." (PMID 18827816, 2008). "It has also been reported that PPARγ agonists suppress tumor cell invasion in colon and breastcancer cells by downregulation of matrix metalloproteinase-7 (MMP-7) andinduction of MMP inhibitors." (PMID 18551185, 2008). "For example, it has been suggested that the mechanism by which endothelial cell proliferation and tumour angiogenesis is inhibited is via the ability of MMP-7, -9, and -12 to convert plasminogen in to angiostatin." (PMID 17311017, 2007). "Recently, MMP-7 has been identified as a sheddase of Fas that induces apoptosis resistance in tumour cells." (PMID 16316466, 2005). "MMP-7 has attracted much attention because it is reported to be present in the tumour invasive front." (PMID 14647147, 2003). "Matrix metalloproteinase-7 (MMP-7) and matrix metalloproteinase-9 (MMP-9) have been reported to have close associations with tumour invasion and metastasis." (PMID 14647147, 2003). "Immunohistochemical staining of β-catenin, E-cadherin and MMP-7 was performed on 51 tumours, including 26 polypoid tumours and 25 ulcerative tumours." (PMID 11953860, 2002). "High MMP-7 levels may also reflect the tumor’s increased potential to invade surrounding tissues and spread." (PMID 41007705, 2025). "MMP-7 has been extensively studied in cancer progression due to its dual role in both extracellular matrix degradation and metastasis promotion, as well as its involvement in the regulation of the Fas/FasL system and apoptosis sensitivity in tumor cells." (PMID 40830621, 2025). "However, other research teams have also found higher AUCs for MMP-7 in other tumor types compared to other routinely used markers (e.g., CA125 or CA15-3)." (PMID 40332487, 2025). "Similarly, MMP7, a matrix metalloproteinase, is known to contribute to tumor invasion and metastasis by degrading extracellular matrix components." (PMID 39628390, 2024). "This spatial proximity suggests a potential interaction where APOE+ TAMs may contribute to the upregulation of MMP7 in cancer cells, thereby facilitating tumour invasion and metastasis." (PMID 39187937, 2024). "Additionally, MMP-7 promotes tumor cell migration by degrading the extracellular matrix, subsequently leading to STAS." (PMID 39830648, 2024). "Subsequently, we examined the clinical importance of MMP7+ tumour cells and CD14+APOE+ cells." (PMID 39187937, 2024). "MIF released from MMP7+ tumour cells activated CD74, CXCR4 and CD44 on immune clusters." (PMID 39187937, 2024). "KIF18A-mediated HCC promotion might be correlated with several abnormally activated signaling pathways, including the Akt/MMP7/9 axis to stimulate tumor invasion and migration, and the CyclinB1-related axis to promote proliferation." (PMID 38433242, 2024). "This quantification revealed that areas with high MMP7+ tumour cells had more CD14+ cells." (PMID 39187937, 2024). "In addition, our investigation revealed the geographical co‐localisation of CD14+APOE+ cells and MMP7+ tumour cells, and examined the intercellular communication between these two cell types." (PMID 39187937, 2024). "In summary, while our study offers significant insights into the spatial structure and functional characteristics of CD14+APOE+ cells and MMP7+ tumour cells in NSCLC, additional research is needed to address these limitations and to further elucidate the mechanisms underlying therapy resistance." (PMID 39187937, 2024).